AR (androgen receptor)
Diseases named in the same sentence as AR in open-access papers (continued):
Sharing a sentence is not in itself a finding about the gene and the disease.
prostate carcinoma (continued). "For this reason, we hypothesized that a new type of AR inhibitor, other than AR antagonists, could serve as a unique therapeutic agent for prostate cancer." (PMID 37744273, 2023). "Moreover, androgen-stimulated/AR-mediated autophagy was shown to promote cell growth and proliferation of prostate cancer cells by augmenting intracellular lipid accumulation into LDs." (PMID 37874216, 2023). "Results confirmed that kaempferol could promote apoptosis of LNCaP (androgen-sensitive human prostate adenocarcinoma cells), AR-positive prostate cancer cells, in a dose-dependent manner." (PMID 37239974, 2023). "The ability of prostate cancer cells to bypass the androgen requirement is multifactorial, but often includes alterations to the androgen receptor (AR), intratumoral androgen stimulation, or crosstalk with alternate pathways that ultimately promote reactivation of AR." (PMID 37520466, 2023). "The phase II QUEST study evaluated NIRA combinations in patients with metastatic castration-resistant prostate cancer who were positive for homologous recombination repair gene alterations and had progressed on 1 prior line of novel androgen receptor-targeted therapy." (PMID 36994854, 2023). "Here, the MAGE11–AR interaction stabilised ligand-free AR expression, which could account for the increased levels of AR frequently observed with recurrent prostate cancer." (PMID 36980267, 2023). "For this reason, the androgen receptor is a significant therapeutic target for prostate cancer." (PMID 37298192, 2023). "Moreover, in a clinical trial with 36 prostate cancer patients, it was observed that low androgen receptor transcriptional activity and higher stemness were tightly linked to a failure in the enzalutamide response, which is in good agreement with our results." (PMID 37958610, 2023). "In summary, we have revealed a mechanism by which prostate cancer cells switch from hormone-dependent growth mediated through AR signaling to hormone-independent growth mediated through EGFR signaling; in addition, we have identified the key regulator as 3-O-sulfated HS produced by HS3ST1." (PMID 37463954, 2023). "Current treatment options for prostate cancer focus on targeting androgen receptor (AR) signaling." (PMID 37142586, 2023). "Estrogen signaling may therefore serve as a surrogate to AR signaling during progression and in hormone-refractory disease, particularly in prostate cancer patients with stromal-rich tumors." (PMID 37965470, 2023). "The AR-activated pathway is known to be essential for the survival of PCa prostate cancer cells." (PMID 36674949, 2023). "It remains unclear whether metabolic regulation of lineage identity can be exploited to promote the reacquisition of luminal features and restore sensitivity to androgen receptor inhibition in prostate cancer." (PMID 38049604, 2023). "Indeed, HSP90 inhibitors have been shown to promote AR degradation in prostate cancer cells and synergize with ADT, but these compounds are less effective in CRPC driven by AR-Vs signaling, such as in C4–2B MDVR and CWR22Rv1 cells." (PMID 36773708, 2023). "AR expression in normal prostate tissues may inhibit CHRM4 expression; however, AR inhibition in advanced prostate cancer after ADT may lead to CHRM4/AKT/MYCN activation, which in turn promotes the NED and invasiveness of prostate cancer cells." (PMID 37142586, 2023). "gDEC did not impact the expression of androgen receptor (AR) or AR-variant 7 (AR-V7) nor sensitize the prostate cancer cells to the anti-androgen enzalutamide in vitro." (PMID 37345101, 2023). "However, even in prostate cancer, AR can have opposing effects on cell cycle regulation, depending on ligand concentration, duration of treatment and the extent of GOF alterations in AR signaling in the context of malignant transformation." (PMID 37102205, 2023). "Furthermore, immunohistology results of prostate cancer showed lower expression of AR and higher expression of MMP9 and FGF11." (PMID 36836690, 2023).
prostate carcinoma (continued). "In addition, many studies have shown that AR signalling can inhibit the sensitivity of prostate cancer to DTX treatment." (PMID 37326412, 2023). "We have published that a prototypic small-molecule Sigma1 inhibitor, IPAG, can be used to suppress aberrant AR signaling in prostate cancer cells, and we also showed that it could induce autophagy in several different cancer cell lines." (PMID 37874216, 2023). "In prostate cancer, overexpression of ~30% of AR co-regulators results from aberrant AR signaling." (PMID 36746939, 2023). "MBOAT2 exhibited specific upregulation in prostate cancer and its expression was positively correlated with androgen receptor (AR) mRNA expression in prostate cancer, suggesting that MBOAT2 may be a target of AR in prostate cancer cells." (PMID 37735316, 2023). "Particularly, the ER and PR in breast cancer and androgen receptor (AR) in prostate cancer." (PMID 36980680, 2023). "Findings in this studyprovide researchers with more specific insights into the propertydistributions, patterns, and scaffold structural information; furthermore,SAR, QSAR modelings, and AC generators can guide further drug discoveryof novel AR antagonists to combat prostate cancer." (PMID 36844574, 2023). "Additionally, this compound inhibits AR expression and arrests the cell cycle in prostate cancer cells." (PMID 37153737, 2023). "In this study, we confirmed that targeting AR could enhance the sensitivity of DTX to prostate cancer cells by upregulating FEN1 expression." (PMID 37326412, 2023). "Here, we explore the phosphatidylinositol-5-phosphate 4-kinases (PI5P4K), a family of lipid kinases that regulate pools of intracellular PI, and demonstrate that the PI5P4Kα isoform influences androgen receptor (AR) signaling, which supports prostate cancer (PCa) cell survival." (PMID 36724278, 2023). "Furthermore, inhibition of both AHR and SRC synergistically reduced androgen receptor (AR) signaling and the growth of prostate cancer cells." (PMID 37696456, 2023). "AR inhibitors such as apalutamide and enzalutamide are a mainstay of prostate cancer therapy." (PMID 36969009, 2023). "In addition, overexpression of the NRP2A isoform in human prostate cancer cells reduces AR protein levels, represses the activity of an AR-responsive reporter construct, and inhibits the expression of AR-target genes." (PMID 37600714, 2023). "ALAN identified direct protein-protein interactions in prostate cancer (AR, HOXB13, and FOXA1)." (PMID 37059746, 2023). "In Prostate cancer, it regulates AR signaling and centrosome-related functions." (PMID 36829467, 2023). "AR signaling also impacts the cellular metabolism reprogramming observed in prostate cancer via binding, together with mTOR, to regulatory regions of the sterol regulatory element-binding transcription factor 1 (SREBF1) gene, which leads to increased expression." (PMID 36768610, 2023). "Actually, we mainly used AR-negative PC-3 and DU-145 for in vitro experiments, so it is indeed unclear whether ARPC1A plays a similar role in AR-positive prostate cancer cells, which is one of the main limitations of this study." (PMID 36814338, 2023). "Moreover, CDK2 mediates androgen-dependent inhibition of AR+, castration-resistant prostate cancer cell proliferation." (PMID 36743211, 2023). "Prostate cancer is highly dependent on androgens and the androgen receptor (AR)." (PMID 36647826, 2023). "Together, these results suggest that AR knockdown inhibits prostate cancer cell proliferation, indicating that AR knockdown could enhance the sensitivity of prostate cancer cells to DTX." (PMID 37326412, 2023). "While the development and growth of prostate cancer can be inhibited by PPARγ agonists, stimulation of PPARγ may also directly lead to the carcinogenicity of prostate cancer via androgen receptor-dependent or -independent pathways." (PMID 37560306, 2023).
prostate carcinoma (continued). "Therefore, metabolic pathways (OXPHOS, amino acids, and lipid metabolism), AR signaling, neuroendocrine metabolism, Myc, and epigenetics drive metabolic reprogramming in prostate cancer and PCSCs." (PMID 37282627, 2023). "As we know, the development of prostate cancers is largely driven by AR signaling." (PMID 37190171, 2023). "In addition, spliced isoforms are responsible for resistance against anticancer therapies, such as androgen receptor (AR)-targeted therapy for prostate cancer." (PMID 37342192, 2023). "AR inhibition can lead to elevated PSMA expression in prostate cancer lesions." (PMID 36604326, 2023). "Next, we investigated whether androgen-induced MALT1 expression facilitates the nuclear translocation of NF-κB signaling in AR-positive prostate cancer cells." (PMID 37047218, 2023). "The FOXA1 pioneer factor is an essential mediator of steroid receptor function in multiple hormone-dependent cancers, including breast and prostate cancers, enabling nuclear receptors such as estrogen receptor (ER) and androgen receptor (AR) to activate lineage-specific growth programs." (PMID 37691854, 2023). "Furthermore, these cells intrinsically express low levels of androgen receptor and its targets, resembling an adenocarcinoma-immune subtype of metastatic castration-resistant prostate cancer." (PMID 37848444, 2023). "Activation of the androgen receptor drives the development of prostate cancer." (PMID 37496005, 2023). "Furthermore, it has been shown that IL-8 plays a role in prostatic cancer progression via promotion of androgen receptor-independent mitogenic pathways." (PMID 36982560, 2023). "Although our SDC models were not supplemented with testosterone, it is possible that testosterone supplementation could have maintained AR expression, as has been shown in prostate cancer PDX models." (PMID 36538240, 2023). "Tight regulation of the AR signaling homeostasis is critical to maintaining diverse cell functions because dysregulation of this homeostasis leads to aberrant androgen responses and promotes prostate cancer." (PMID 37216013, 2023). "Targeting of AR signaling in prostate cancer cells has been the prime focus." (PMID 37282627, 2023). "The fact that AR inhibitors have recently been approved for the treatment of prostate cancer and could be a therapeutic tool for certain subgroups of breast cancer will increase the focus on their study (including radiomics)." (PMID 37189515, 2023). "Considering the importance of androgen and AR signal in the development of prostate cancer and the progression of prostate cancer, CSS-FBS medium, which depleted androgen in the medium, was used to explore the effect of TPM2 on androgen level reactivity in PCa cells." (PMID 36823643, 2023). "A proteomic profiling of the mTOR complex bound to chromatin in different prostate cancer cell lines shows the androgen-dependent binding of the AR and the additional important function of the nucleosome remodeling deacetylase NuRD complex for the regulation of gene expression." (PMID 36768610, 2023). "AR phosphorylation at S16, S81, S256, S308, S424, and S650 increases in the presence of androgen activation, while S94 is constitutively phosphorylated in prostate cancer (PCa) cells." (PMID 38203649, 2023). "However, a recent report showed a contrary relevance between AR and NF-κB by comparing human prostate cancer cells and mouse prostate tissues." (PMID 37047218, 2023). "Moreover, in prostate cancer cells it has been described an effect of androgens on AR (androgen receptor) increasing TMPRSS2 expression, suggesting the correlation of increased lung infections (and severe COVID-19) in men." (PMID 37287057, 2023). "In addition to its use in castration-resistant prostate cancer, abiraterone has also shown activity in other AR-positive malignancies, such as salivary gland carcinomas, when combined with LHRH analogs." (PMID 37686423, 2023).
prostate carcinoma (continued). "As a result of the dynamic cooperation between FOXA1 and nuclear receptor function, loss of FOXA1 expression is sufficient to restrict ER and AR transcriptional activity, cell proliferation, and tumor growth in ER+ breast cancers and AR+ prostate cancers, respectively." (PMID 37691854, 2023). "Likewise, it was reported that the expression of TMEM158 had a very negative correlation with the expression of the androgen receptor (AR), suggesting that the AR pathway negatively modulates the expression of TMEM158 in prostate cancers." (PMID 37936608, 2023). "AR plays an essential role in the proliferation and development of prostate cancer." (PMID 37375731, 2023). "Persistent androgen receptor (AR) signalling is the main driver of prostate cancer (PCa)." (PMID 36937454, 2023). "The androgens/androgen receptor (AR) axis is the main therapeutic target in prostate cancer (PCa)." (PMID 37892208, 2023). "Androgen receptor (AR) inhibition is standard of care for advanced prostate cancer (PC)." (PMID 37636316, 2023). "Few studies have investigated the association between AR and FEN1 in prostate cancer." (PMID 37326412, 2023). "Analysis of CHRM4-driven IFNA17 cytokine release in the prostate cancer TME following ADT resistance may provide a clear understanding of the feedback loop consisting of CHRM4/AKT/MYCN in the context of AR inhibition." (PMID 37142586, 2023). "Androgen receptor (AR) signaling plays a key role in prostate cancer (CaP) pathogenesis." (PMID 36937838, 2023). "hnRNPK inhibits the translation of AR mRNA in prostate cancer." (PMID 36735291, 2023). "Notably, the upregulation of transcription factors of GR, BRN2, TBX2, and NR2F1 was found to mediate the resistance to enzalutamide in CHD1-deficient prostate cancer, since inhibition of each factor re-sensitizes CHD1 loss prostate tumors to AR inhibitor." (PMID 36776288, 2023). "Androgen receptor (AR) variants, especially AR3, could contribute to prostate cancer progression through inducing EMT, achieving stem cell characteristics, and regulating stem cell related pathways." (PMID 38002944, 2023). "Prostate cancer is largely driven by androgen receptor (AR) signaling." (PMID 36776288, 2023). "Studies have illustrated the crosstalk between AR and NF-κB in which the transcriptome in the cells of prostate cancer may be reprogrammed." (PMID 37047218, 2023). "In this exploratory study that prospectively enrolled 9 patients with metastatic castration-resistant prostate cancer initiating a new ARSi, we found a heterogeneous response to the AR pathway modulation and in most cases discordance between PSA kinetics and whole-body PSMA PET measurements." (PMID 37902861, 2023). "Silencing LCMT1 increases AR activity and promotes castration-resistant prostate cancer growth." (PMID 37644036, 2023). "AR is a critical factor contributing to prostate cancer development and progression." (PMID 37612283, 2023). "However, the emerging castration-resistant prostate cancer (CRPC) during cell-autonomous androgen receptor (AR) signaling complicates the progression of prostate cancer." (PMID 37047218, 2023). "Additionally, we touch on the various targets for PROTAC in prostate cancer, including the androgen receptor (AR) and other critical oncoproteins, and discuss the future prospects and challenges in this field." (PMID 37175108, 2023). "The AR signaling axis drives prostate cancer cell growth and survival." (PMID 37646236, 2023). "Taken together, these results indicate that AR knockdown may enhance the chemosensitivity of prostate cancer cells by downregulating FEN1 through the ERK/ELK1 signalling pathway." (PMID 37326412, 2023). "The results from AR reporter assays and gene expression analyses of AR target genes in prostate cancer cell lines support the hypothesis that CT7001 represses transcription mediated by both full-length AR and truncated, constitutively active AR-Vs in vitro." (PMID 37076563, 2023).
prostate carcinoma (continued). "Prostate cancer is often treated by perturbing androgen receptor signalling." (PMID 36949059, 2023). "An epigenetic transition to CRPC induced by the action of AR-mediated androgen could be speculated in the patients with prostate cancer." (PMID 37025180, 2023). "AR-Vs could play a potential role in primary and acquired resistance to conventional and next-generation hormonal therapies in prostate cancer and therefore have gained momentum." (PMID 36983083, 2023). "Therefore, MED19 is crucial in controlling specific gene subsets and directs prostate cancer survival and proliferation by regulating AR transcriptional activity." (PMID 37880276, 2023). "However, the progression towards castration-resistant prostate cancer is inevitable, as the cancer cells reactivate androgen receptor signaling and adapt to the castrate state through autoregulation of the androgen receptor." (PMID 37509723, 2023). "PPARγ activation by rosiglitazone may also reduce the action of androgen receptor in androgen-dependent prostate cancer cells." (PMID 37560306, 2023). "Ubiquitin proteasome activity is suppressed in enzalutamide resistant prostate cancer cells, and the heat shock protein 70/STIP1 homology and U-box-containing protein 1 (HSP70/STUB1) machinery are involved in androgen receptor (AR) and AR variant protein stabilization." (PMID 36773708, 2023). "To investigate the adaptations of drug-resistant prostate cancer cells, we adapted the prostate tumoral cell line LNCaP, which is androgen-sensitive, to grow in the presence of the androgen receptor antagonist 2-hydroxy-flutamide (FLU) via a stepwise increase in its concentration for nine months." (PMID 37958610, 2023). "We hypothesized that a new type of AR inhibitor, other than AR antagonists, could serve as a unique therapeutic agent for prostate cancer." (PMID 37744273, 2023). "Moreover, in AR-positive CWR22rv1 prostate cancer cell-bearing mice, fisetin inhibits tumor growth and decreases serum PSA levels." (PMID 37216013, 2023). "When AR was knocked down in prostate cancer cells, FEN1 expression was also downregulated." (PMID 37326412, 2023). "Recent studies showed that AR could undergo phase separation and form transcriptionally active condensates to stimulate oncogenic transcription programs in androgen-dependent prostate cancer cells." (PMID 37265348, 2023). "At the same time, KDM4B was the first identified androgen receptor AR)-regulated demethylase with effects on AR signaling and turnover and might be a therapeutic target for prostate cancer." (PMID 36755810, 2023). "The AR signaling pathway plays a crucial role in prostate cancer growth and survival." (PMID 37686423, 2023). "However, the effect of FEN1 on docetaxel (DTX) sensitivity and the regulatory mechanisms of AR on FEN1 expression in prostate cancer need to be further studied." (PMID 37326412, 2023). "Currently, PROTACs are designed to target the AR in prostate cancer." (PMID 37175108, 2023). "Furthermore, it has been shown that growth factor receptors, including EGFR, cross-talk with androgen receptor in prostate cancer and epithelial cells." (PMID 36879303, 2023). "Therefore, tumor expression of FOXA1 in ER+ breast and AR+ prostate cancers is often a predictive indicator of sensitivity to nuclear hormone receptor–targeted therapies." (PMID 37691854, 2023). "CARM1 directly interacts with β-Catenin, and because there is crosstalk between AR and β-Catenin in castration-resistant prostate cancer, these cancers may be vulnerable to CARM1i." (PMID 37536629, 2023). "In addition, the AR-PROTAC inhibits the proliferation of enzalutamide-resistant prostate cancer patient-derived xenograft (PDX) tumors." (PMID 38203649, 2023). "Moreover, AR is found in a complex with FLNA, and the AR/FLNA complex was suggested to be a target in the prostate cancer microenvironment, for example, by using an AR-derived stapled peptide, which disrupts the AR/FLNA complex assembly." (PMID 38255186, 2023).